GPHRB (golgi pH regulator B)
Description:
Voltage-gated channel that enables the transfer of anions such as iodide, chloride, bromide and fluoride which may function in counter-ion conductance and participates in Golgi acidification. Plays a role in lymphocyte development, probably by acting as a RABL3 effector in hematopoietic cells (By similarity). Essential for maintaining the acidic luminal pH of the Golgi apparatus in neurons, which is important for preserving Golgi structural integrity (By similarity). This integrity supports proper axonal transport and synaptic maintenance in cerebellar inhibitory neurons, including Purkinje and basket cells (By similarity). Additionally, Golgi acidification facilitates the activation of SREBP2, thereby ensuring sufficient cholesterol biosynthesis necessary for normal neuronal morphology and function (By similarity).
Synonyms: GPHR; GPR89; GPR89B; GPR89C; SH120; LINC02804; UNQ192
Tractability: Antibody: UniProt predicts a signal peptide or a membrane-spanning region. PROTAC: ubiquitination databases record sites on it.
Gene: Protein-coding gene on chromosome 1 (147,928,393 to 147,993,592, forward strand). Ensembl gene ENSG00000188092.
Subcellular location: Golgi apparatus membrane
Subcellular location (Human Protein Atlas): Endoplasmic reticulum
Gene Ontology:
Molecular function: protein binding; voltage-gated monoatomic anion channel activity
Biological process: cholesterol homeostasis; intracellular pH reduction; T cell differentiation; monoatomic anion transmembrane transport
Cellular component: Golgi membrane; Golgi cisterna membrane; membrane
Genetic constraint (gnomAD): Loss-of-function variants: 12 observed, 14.94 expected, observed/expected ratio (o/e) 0.8, 90% interval 0.51 to 1.3. The synonymous counts are far from expectation, so gnomAD's model fits this gene poorly and the ratio says little. Missense variants: 62 observed, 131.75 expected, observed/expected ratio (o/e) 0.47, 90% interval 0.38 to 0.58. Synonymous variants: 20 observed, 46.51 expected, observed/expected ratio (o/e) 0.43, 90% interval 0.3 to 0.62.
Homologues: Orthologues: chimpanzee GPR89A (100% identical), macaque GPR89A (99% identical), dog GPR89A (98% identical), mouse Gpr89 (97% identical), rat Gpr89b (97% identical), zebrafish GPR89A (90% identical), tropical clawed frog gpr89b (87% identical), Caenorhabditis elegans gphr-1 (56% identical), Drosophila melanogaster GPHR (56% identical), Caenorhabditis elegans gphr-2 (54% identical). Paralogues in human: GPHRA (100% identical).
Diseases named in the same sentence as GPHRB in open-access papers:
GPHRB is named in the same sentence as 5 diseases in open-access papers, as found by Europe PMC text mining. Sharing a sentence is not in itself a finding about the gene and the disease.
GPHRB shares sentences with these, for which no sentence is quoted: Cirrhosis (1 paper); congenital hypothyroidism (1); Hepatitis (1); malaria (1); microcephaly (1).